KLF5 (KLF transcription factor 5)
Diseases named in the same sentence as KLF5 in open-access papers (continued):
Sharing a sentence is not in itself a finding about the gene and the disease.
tumor (continued). "KLF5, a stem-related transcription factor, plays an important role in tumor cell proliferation, survival, apoptosis, and drug sensitivity." (PMID 35379798, 2022). "KLF5's role in cancer is context-dependent; in most malignancies, it serves as an oncogene, whereas in others, it has tumor-suppressive properties." (PMID 35345512, 2022). "We then performed RNA sequencing to profile transcriptome of the four tumor foci and noticed that KLF5 was also the top 1 transcription factor correlated with EPHA2 in the four samples." (PMID 35105853, 2022). "Through analyzing the copy number variation data of a large cohort of tumors from 33 different cancer types, we found opposite changes in CNV of KLF5 occurred in different tumor types." (PMID 33923166, 2021). "The Kruppel-like factor 5 (KLF5) gene has been reported to function as a tumor suppressor, which inhibits cell invasion and migration in numerous types of cancers." (PMID 34066762, 2021). "Mechanistically, by targeting KLF5, miR‐9 regulates the expression of the transcription factor Sp1 that, in turn, stimulates tumor growth and confers resistance to RT+CTX in vitro and in vivo." (PMID 34062049, 2021). "KLF4 and KLF5 were differentially expressed in normal and tumor tissues of the gastrointestinal tract, and their differential expression is related to several genes or pathways." (PMID 34367275, 2021). "Although KLF5-null (KLF5–/–) cells had negligible (PC-3 and DU 145) or significantly slowed (C4-2B) tumor growth in the bone, they were able to propagate in vitro." (PMID 33731701, 2021). "Our data have validated that KLF5 knockdown accelerated GC cell autophagy in vitro and repressed tumor growth in vivo by regulating the DANCR/miR-194/AKT2 axis." (PMID 34548487, 2021). "Here, we describe a new signaling axis, involving EGFR, miR‐9, KLF5, and Sp1, that connects the tumor stem‐like features of HNSCC with the response to therapy." (PMID 34062049, 2021). "One is the epithelial state induced and maintained by deacetylated KLF5, in which cells are more rapid in proliferation and tumor formation, ineffective in the induction of bone metastatic lesions, and more sensitive to the therapeutic effect of docetaxel." (PMID 33731701, 2021). "The upregulation of KLF5 has been previously demonstrated in GC tissues and cells, which resulted in tumor aggressiveness." (PMID 34548487, 2021). "Copy number variation (CNV) of KLF5 is prevalent in different tumor types, according to a previous study." (PMID 33923166, 2021). "In summary, this study revealed that KLF5 underwent amplification or deletion in different tumor types, which led to up- or downregulation of KLF5 mRNA expression accordingly." (PMID 33923166, 2021). "This is probably because KLF5 expression was correlated with the T stage of tumor and the Lauren classification, which was suggestive of the potential biological roles played by KLF5." (PMID 33923166, 2021). "In pan-cancer of 33 tumor types, the KLF5 gene showed both amplifications and deletions in different tumor types." (PMID 33923166, 2021). "We found that higher expression of KLF5 correlated with larger tumor size (p = 0.008) and later tumor (T) stage (p = 0.029)." (PMID 33923166, 2021). "KLF5-regulated cell plasticity is likely a crucial mechanism for cancer cells to survive stresses from tumor microenvironments, including the bone microenvironment and chemotherapy-mediated stresses." (PMID 33731701, 2021). "Recently, it has been shown that depletion of KLF5 substantially inhibits the tumour growth, proliferation and survival of basal TNBC cells in vivo." (PMID 34799978, 2021). "UALCAN was adopted to analyze the changes in the methylation levels of KLF4 and KLF5 promoters between normal and tumor tissues of the gastrointestinal tract." (PMID 34367275, 2021).
tumor (continued). "We measured nude mouse tumors for 4 consecutive weeks to draw growth curves, and the data illustrated that silencing KLF5 can inhibit tumor growth (p < 0.001) and reduce tumor weight (p < 0.001)." (PMID 34548487, 2021). "In gastrointestinal tumors, changes in the expression levels of KLF4 and KLF5 have an impact on tumor development." (PMID 34367275, 2021). "In summary, this study provides clinical evidence that KLF5 is widely upregulated in PTC tumor tissues and provides mechanistic evidence for tumorigenic role of KLF5, as well as its role in tumor progression, metastasis and stemness in PTC." (PMID 33430300, 2021). "Consistently, tumor cells expressing KLF5 or KLF5KQ gave rise to more severe bone lesions than those expressing KLF5KR or EV as indicated by radiographs of tumor-bearing tibias." (PMID 33731701, 2021). "PVT1 was reported to regulate cell proliferation and tumor growth in triple-negative BC through KLF5/ beta-catenin signaling." (PMID 34922601, 2021). "The other is the mesenchymal state maintained by Ac-KLF5, which makes cells slower in cell proliferation and tumor growth, potent in the induction of bone metastatic lesions, and resistant to docetaxel." (PMID 33731701, 2021). "Meanwhile, the IHC results of tumor tissues also demonstrated that Klf5 and Nrf1 expression were down-regulated with metapristone treatment." (PMID 33413440, 2021). "Collectively, these results support a role for KLF5 in opposing AR to promote features of basal cell identity, which precedes the emergence of neuroendocrine hallmarks and castration-resistant tumor growth in a model of NEPC progression." (PMID 34737261, 2021). "Expression of the proliferation marker Ki67 was low in KLF5-null tibial tumors, consistent with the necessity of KLF5 for tumor growth in the tibia." (PMID 33731701, 2021). "While expression of KLF5KQ induced both sphere-forming and tumorigenic abilities, expression of KLF5 or KLF5KR caused more and larger spheres and more rapid tumor growth." (PMID 33731701, 2021). "KLF5-induced BBOX1-AS1 exerts tumor-promotive roles in NSCLC via sponging miR-27a-5p to activate MELK/FAK signaling, providing the possibility of employing BBOX1-AS1 as a therapeutic target for NSCLC patients." (PMID 33931086, 2021). "Intriguingly, more TRAP-positive (TRAP + ) cells indeed formed at the tumor-bone interfaces by DU 145, PC-3, and C4-2B tumor cells carrying either KLF5 or KLF5KQ, indicating that KLF5 acetylation in tumor cells promotes osteoclastogenesis." (PMID 33731701, 2021). "It has been proposed that KLF5 can act either as tumor suppressor or oncogene, depending on the tissue and cellular context." (PMID 34062049, 2021). "Perhaps by regulating the expression of KLF5, it can reduce tumor metastasis and play an anticancer role." (PMID 34367275, 2021). "Second, it also demonstrates that KLF5 downregulation inhibits tumor growth by increasing apoptosis, as revealed by the downregulation of anti-apoptotic factors, bcl-2 and bcl-xL as well as cleavage of PARP and caspase-3 in both PTC cell lines." (PMID 33430300, 2021). "The TFs that appeared more than four times in tumor samples were defined as malignant tumor-conservative TFs including Fral, KLF5, and NFY, while TFs that appeared only once were defined as specific TFs such as POU2F2." (PMID 34722892, 2021). "To further verify the tumor metastasis-suppressive role of KLF5 in PCa in vivo, we established metastasis mouse models using the tail-vein injection of 22RV1 sublines (22RV1-NC/22RV1-shKLF5)." (PMID 32546700, 2020). "Of note, although CDX1 and CDX2 were found to be both inactivated and underexpressed, several TFs such as KLF5 or ATOH1 with established tumor suppressor roles in colorectal cancer were only found inactivated via SCIRA." (PMID 33083012, 2020). "Consistent with colony and sphere formation results, KLF5 silencing reduced tumor growth, as indicated by tumor images and tumor weights at excision." (PMID 32245249, 2020).
tumor (continued). "In the same tumour sets, the expression levels of target molecules (KLF5, TFDP1 and MDM2) decreased at the mRNA and protein levels." (PMID 32066912, 2020). "Specifically, KLF5 silencing significantly attenuated the functions of AR in the maintenance of colony and sphere formation in vitro and xenograft tumor growth in nude mice." (PMID 32245249, 2020). "KLF5 overexpression was noted in 53.9% (229/425) of EOC cases and was associated with older age (p = 0.0070), larger tumor size (p = 0.0001), distant metastasis (p = 0.0001) and stage IV tumors (p < 0.0001)." (PMID 33424607, 2020). "A recent study showed KLF5 disruption can reduce STAT3 activation, and cause tumor regression in vivo." (PMID 33424607, 2020). "Silencing KLF5, in turn, reduced AR transcriptional activity and inhibited androgen-induced cell proliferation and tumor growth in vitro and in vivo." (PMID 32245249, 2020). "In the tumor xenografts, IHC staining demonstrated enzalutamide treatment reduced the expression of both KLF5 and AR, which is consistent with in vitro findings, and KLF5 silencing also downregulated AR expression." (PMID 32245249, 2020). "Enzalutamide treatment also reduced tumor growth, and KLF5 silencing and enzalutamide had an additive effect on tumor growth." (PMID 32245249, 2020). "We detected lower KLF5 mRNA expression in metastatic tumor tissues than in localized tumor tissues of PCa as evidenced by the analysis from GSE36988, GSE6919, and EXP00230, indicating that KLF5 was downregulated in metastatic loci of PCa." (PMID 32546700, 2020). "Survival analysis using data from The Cancer Genome Atlas showed that patients highly expressing KLF5 exhibited shorter overall and tumor-free survival times." (PMID 31327760, 2019). "We found the tumor weights in the CW22RV1/shKLF5 (KLF5-KD) group (222.5 ± 61.82 mg, n = 9) to be dramatically higher than those in CW22RV1/shNC (NC) group (107.125 ± 26.36 mg, n = 9)." (PMID 31534497, 2019). "As with overall survival, patients exhibiting low KLF5 expression had significantly better tumor-free survival times after surgery than those exhibiting high KLF5 expression." (PMID 31327760, 2019). "Altogether, these data indicate that Klf5 is a tumor suppressor through the promotion of apoptosis of p190-BCR-ABL B-ALL." (PMID 30038712, 2018). "Recent data supports the function of KLF5 as an oncogene or tumor suppressor in carcinogenesis depending on the cellular and genetic context in which it operates." (PMID 30038712, 2018). "Both KLF4 and KLF5 interact with the same cis-element, inhibit each other’s activity, and they also exhibit tumor suppressor and oncogenic activities, respectively." (PMID 29914355, 2018). "The Krüppel-like factor (KLF) KLF5 is a DNA-binding transcriptional regulator that is involved in the tumor-initiating properties of cancer stem-like cells, migration, and drug resistance." (PMID 29772686, 2018). "Altogether, these results indicate that the Klf5 axis acts as a tumor suppressor by promoting GSH depletion and glutathione-S-transferase mediated glutathionylation." (PMID 30038712, 2018). "After Klf5 gene deletion induction (arrows), we found that Klf5 expression extended the survival of Klf5∆/∆ leukemic mice, which supports the role of Klf5 as a tumor suppressor in p190 BCR-ABL transformed B-ALL." (PMID 30038712, 2018). "As a DNA-binding transcriptional factor, KLF5 has been shown to have essential roles in multiple cellular processes, including tumor progression, cell proliferation, differentiation and apoptosis, in different human cancers." (PMID 29898734, 2018). "miR-153 is an ancient and conserved miRNA which suppresses the tumor development by downregulating tumor-associated genes, such as SNAI1, KLF5, and MCL-1." (PMID 29959560, 2018). "In this study, we demonstrated that KLF5, as a tumor suppressor, was suppressed by DNMT1-maintained hypermethylation in ccRCC." (PMID 28749461, 2017).
tumor (continued). "KLF5 is transcriptionally regulated by several hormones, including androgen and progesterone, which contribute to hormone-driven tumor progression." (PMID 28030791, 2017). "In this study, we demonstrated a potential role for tumour necrosis factor receptor superfamily member 11a (TNFRSF11a), the corresponding gene of which is a direct binding target of KLF5, in tumour cell proliferation and invasiveness." (PMID 29146991, 2017). "Photon fluxes of lungs with KLF5-expressing tumor nodules decreased compared with that in control group." (PMID 28749461, 2017). "Collectively, our data demonstrate that KLF5 inhibits ccRCC growth as a tumor suppressor and highlight the potential of 5-Aza-CdR to release KLF5 expression as a therapeutic modality for the treatment of ccRCC." (PMID 28749461, 2017). "Consistent with the anti-proliferation effects in ccRCC cell lines, tumor growth of 786-O xenograft was significantly impaired accompanied with KLF5 expression." (PMID 28749461, 2017). "Protein levels of KLF5 were dramatically reduced in tumor areas than in adjacent normal renal tubule tissues." (PMID 28749461, 2017). "Whereas RB1 is a well-established tumor suppressor gene at 13q14, the tumor suppressor function of KLF5 has also been demonstrated in both xenograft and knockout models." (PMID 25896712, 2015). "In that study, enhanced cell proliferation was identified as a mechanism for the tumor promoting effect of Klf5 deletion." (PMID 25896712, 2015). "In conclusion, BAP1 is a KLF5 DUB and BAP1 promotes basal breast cell proliferation, migration, tumour growth and metastasis partially through stabilizing KLF5." (PMID 26419610, 2015). "In vitro cultured cells eliminate any effects of tumor growth in vivo, thus providing evidence for a direct effect of KLF5 on angiogenesis." (PMID 25896712, 2015). "Transient overexpression of KLF5 partially but significantly rescued the BAP1 knockdown-induced tumour growth suppression." (PMID 26419610, 2015). "Hemizygous deletion induces haploinsufficiency of KLF5, and our recent publication demonstrated that hemizygous deletion of Klf5 in mouse prostates indeed promotes tumor development." (PMID 25896712, 2015). "On the other hand, interruption of KLF5 acetylation converts its function from that of a tumor suppressor to a tumor promoter, and multiple oncogenic pathways appear to be involved." (PMID 25896712, 2015). "KLF5 can function as a tumor suppressor or a tumor promoter, depending on the cell- and tissue-specific context." (PMID 23372710, 2013). "In intestinal cells, KLF5 promotes tumor progression and mediates intestinal epithelial cell hyperproliferation and regenerative responses in response to infection and chronic inflammation." (PMID 23372710, 2013). "For example, TGF-β is a potent tumor suppressor in early stage tumorigenesis but becomes a promoter in late stage tumor progression; and deacetylation converts KLF5 from an anti-proliferative factor to a pro-proliferative in epithelial cells." (PMID 22569290, 2012). "The reduction in tumor number in ApcMin/KRASV12/Klf5+/- mice was also statistically significant compared to ApcMin mice alone, with a 75% decrease." (PMID 20298593, 2010). "In accordance, KLF4 is a putative tumor suppressor in B-cell malignancies, whereas KLF5 confers drug resistance to acute lymphoblastic leukemia by promoting survivin expression." (PMID 20119532, 2009). "Globally, KLF4 and KLF6 are considered as tumor suppressor gene, whereas KLF5 promotes cell proliferation." (PMID 20119532, 2009). "Targeting KLF5 results in cell proliferation, transformation and multi-cellular tumor spheroids (MCTS) inhibition." (PMID 20119532, 2009). "Some genes, such as MIF and CCDN2, bore predominant pro-tumor progression functions, other genes, such as KLF5 and TGFBR2, contribute to tumor suppression functions." (PMID 18570662, 2008). "In this study, Vimentin serves as an important bridge between KLF5 and tumor cell stemness." (PMID 40307891, 2025).
tumor (continued). "Further analysis of the TCGA pan-cancer dataset demonstrated that significant differences in KLF5 gene expression between tumor tissues and their corresponding normal tissues were observed in both paired and unpaired samples for BRCA, CHOL, KICH, KIRC, LUSC, PRAD, STAD, and UCEC." (PMID 41583492, 2025). "In contrast, only a few of cancer types demonstrated correlations on microsatellite instability (MSI), and none exhibited statistically significant links between KLF5 expression and tumor mutational burden (TMB)." (PMID 41583492, 2025). "However, the use of KLF5 as a new tumor marker was superior to AFP in terms of specificity and sensitivity, with complementary diagnostic value for HCC, especially in patients with low AFP levels." (PMID 40697993, 2025). "KLF5 can also regulate the expression of downstream tumor-related molecules." (PMID 40936898, 2025). "KLF5 is mainly expressed in cancer cells among the multiple cellular components of tumor tissue." (PMID 39827156, 2025). "Moreover, our scRNA‐seq analysis revealed a significant increase in KLF5 expression in liver metastatic tumor cells." (PMID 39985269, 2025). "However, TAZ/YAP can protect KLF5 from WWP1-mediated degradation by binding to KLF5 through its WW domain, thereby promoting BC cell proliferation, survival, and tumor growth." (PMID 40535763, 2025). "A previous study described that KLF5 deletion could promote anti‐tumor immunity by enhancing the proliferation and function of CD4+ and CD8+ T cells." (PMID 39720765, 2025). "Numerous studies have also confirmed the close relationship between KLF5 and tumor cell stemness." (PMID 40307891, 2025). "Importantly, further investigations are warranted to identify the specific WW domain within MAGI2 that binds to KLF5, potentially offering a novel target for regulating tumor fatty acid synthesis." (PMID 39169280, 2024). "KLF5 may regulate VEGFA, a KLF5 target that mediated KLF5’s role in angiogenesis, expression, and tumor angiogenesis in vivo." (PMID 38602556, 2024). "One allele of Klf5KR knockin appeared insufficient to promote organoid formation, implying that the extent of Klf5 acetylation may be an essential factor in suppressing tumor growth." (PMID 38781024, 2024). "KLF5 overexpression increased tumor growth and chemotherapeutic drug resistance." (PMID 37588224, 2024). "We then established pancreatic xenograft tumor models to further determine whether inhibition of KLF5 sensitizes PDACs to PARP inhibitorsin vivo." (PMID 38433576, 2024). "This epigenetic modulation by acetylated KLF5 unveils a therapeutic opportunity; the concurrent administration of docetaxel and the CXCR4 inhibitor plerixafor has shown efficacy in curbing ac‐KLF5‐driven bone metastasis and enhancing tumor response to chemotherapy." (PMID 38374872, 2024). "By promoting the phosphorylation of PI3K and AKT, KLF5 acts as a tumor inducer." (PMID 36761967, 2023). "Given its pro-proliferative functions in several cell types, whether KLF5 is tumor-suppressive or oncogenic in ESCC remains debatable." (PMID 38087142, 2023). "In fact, this exciting relationship between KLF9's function and the status of essential oncogenes or tumour suppressors is reminiscent of the findings of KLF5, suggesting that this could be, to some level, a common phenomenon of the KLF family." (PMID 37400979, 2023). "Moreover, the elevated KLF5 level was closely related to aggressive tumor phenotypes, including poor differentiation and distant metastases." (PMID 38087142, 2023). "Furthermore, considering the significance of KLF4 and KLF5 in tumor formation and development, efforts to understand their context-dependent role and downstream effectors, interacting proteins, and response to chemotherapy drugs are essential." (PMID 37173904, 2023).